IDH1 (isocitrate dehydrogenase (NADP(+)) 1)
Diseases named in the same sentence as IDH1 in open-access papers (continued):
Sharing a sentence is not in itself a finding about the gene and the disease.
glioblastoma (1,109 papers, 2009 to 2026). The most malignant astrocytic tumor (WHO grade IV). "Diffuse gliomas are primary brain tumors including glioblastomas (GB), astrocytomas, and oligodendrogliomas, the latter two harboring IDH1 mutations and exhibiting slower progression." (PMID 42026941, 2026). "An IDH1 mutation is caused by a point mutation, which distinguishes glioblastoma from astrocytoma and oligodendroglioma." (PMID 41002991, 2025). "Prior to CNS5, studies estimated the frequency of IDH1 mutations in primary glioblastoma at 5–7%, whereas 11.6% of our cohort was IDH1-mutant." (PMID 40261557, 2025). "It has been shown that overexpression of WT IDH1 has been implicated in glioblastomas, leading to increased tumor cell growth, metabolic reprogramming including lipid biosynthesis, and decreased survival in in vivo models." (PMID 40188944, 2025). "These enzymes were thought to be strictly associated with cellular metabolism until 2008, when genetic profiling of glioblastoma samples revealed the presence of IDH1 mutations in 12% of the analyzed samples, which originated from younger patients." (PMID 40867259, 2025). "Despite these associations, grade 4 IDH1/2-mutant astrocytomas demonstrated significant genomic distance from glioblastomas, reinforcing their distinct categorization from glioblastoma." (PMID 39164213, 2025). "Our results support further studies combining ONC201 or ONC206 with RT and TMZ (IRT) in wildtype IDH1 glioblastoma, H3K27M mutated diffuse gliomas, or other tumors." (PMID 40145650, 2025). "Extracellular vesicles derived from glioblastoma cells with the IDH1 mutation have been reported to have a difference in lipid profile compared to normal cells." (PMID 40761875, 2025). "To study the influence of immune composition on PFS in glioblastoma patients we performed a Cox regression analysis on the group of patients with a glioblastoma, stratified on dexamethasone treatment and corrected for sex, age, and IDH1 mutation status." (PMID 38318180, 2024). "In glioblastoma, IDH1 mutations are more common in younger patients and in those diagnosed with a secondary glioblastoma." (PMID 39767640, 2024). "Oncogenic mutations to IDH1 were identified in 2008 following an integrated genomic analysis of glioblastoma multiforme (GBM), and have since been targeted with pharmaceutical inhibitors." (PMID 39596840, 2024). "Among these pivotal biomarkers, IDH1/2 somatic variants are critical in confirming the diagnosis of glial tumors, including glioblastoma, and distinguishing them from lower-grade counterparts." (PMID 39744115, 2024). "Considering IDH1 mutations have been linked to higher survival in glioblastoma patients, the longest-surviving female cluster is consistent with this theory." (PMID 38893240, 2024). "Telomerase reverse transcriptase promoter (TERTp, HGNC:11730) mutations are frequent in multiple tumor types, and are present in 70–80% of glioblastomas and around 80% of oligodendrogliomas, where they always co-occur with IDH1/2 mutations." (PMID 38398126, 2024). "G0S2 was identified as a prospective biomarker in glioblastoma stem-like cells, and the methylation-induced downregulation of G0S2 was linked to the inhibited invasion of IDH1-mutant glioblastoma cells and an improved prognosis." (PMID 38672263, 2024). "Adult secondary glioblastoma multiforme (GBM) harbours isocitrate dehydrogenase 1/2 (IDH1/2) mutations (about 98%), which are rarely found in childhood GBM, and also regulate methylation at the H3K27 and H3K36 residues." (PMID 39439908, 2024). "IDH1 R132H mutation introduced to U87MG glioblastoma cells was shown to decrease the migration speed on Matrigel and collagen IV substrates compared to the wild-type." (PMID 39596246, 2024).
glioblastoma (continued). "The work revealed significant genetic modifications, including isocitrate dehydrogenase (IDH1) mutations, which play a crucial role in glioblastoma development." (PMID 38807869, 2024). "MGMT methylation is also associated with IDH1 mutant tumours and therefore is more common in secondary than in primary glioblastoma (75% vs. 36% respectively)." (PMID 39767640, 2024). "Having a glioblastoma diagnosis was less likely to be associated with IDH1 mutation (OR 0.02, 95% CI 0.01–0.04)." (PMID 39767640, 2024). "In our study, patients were divided into different groups depending on the brain tumor’s histopathological subtypes and tumor grade, finding a higher rate of IDH1 mutation (AF%) in the diffuse astrocytoma, glioblastoma and oligodendroglioma." (PMID 38172718, 2024). "IDH1 mutation alters the epigenetic landscape and is associated with a more favorable outcome in glioblastoma." (PMID 38672566, 2024). "Higher proportions of IDH1 mutations have been reported in low-grade astrocytomas compared with those in primary glioblastomas and oligodendrogliomas." (PMID 38919539, 2024). "The IDH1 R132 mutation was found in 10% of the glioblastomas, 43% of the astrocytomas WHO III, and 77% of the astrocytomas WHO II." (PMID 38318180, 2024). "IDH1 mutations occur in lower-grade astrocytomas and secondary glioblastomas affecting young patients with a generally good prognosis." (PMID 38240992, 2024). "We further analyzed OS according to mutational profile for patients with glioblastoma as a more homogeneous group, to exclude strong prognostic factors such as disease grade and the presence of IDH1/2 mutation." (PMID 39684714, 2024). "Of the total cohort, 26 patients had wild-type glioblastomas, while 3 patients had the IDH1 mutation." (PMID 37369744, 2023). "Mutation in the IDH1 gene has been found in many genetic conditions and cancer types, such as acute myeloid leukemia, glioblastoma, and myelodysplastic syndromes." (PMID 37671046, 2023). "EGFRvIII-positive brain tumors were all glioblastoma with wild-type IDH1/2 status, most with EGFR amplification and EGFR mutation." (PMID 38201434, 2023). "Mutations in the isocitrate dehydrogenase genes 1 and 2 (IDH1/IDH2) define a glioma subtype associated with improved patient outcome in comparison to IDH-wildtype gliomas with molecular features of glioblastoma." (PMID 36739454, 2023). "For example, targeted therapies like ivosidenib and enasidenib have shown promise in inhibiting the mutant IDH1 protein, which drives tumour growth in glioblastoma cases with IDH1 gene mutations." (PMID 37811056, 2023). "Several studies have shown that the presence of an IDH1 mutation in patients with glioblastoma heightens the likelihood of epilepsy development." (PMID 38067243, 2023). "Approximately 20–30% of point mutations in glioblastomas occur in IDH1 and, to a lesser extent in IDH2, which are enzymes involved in cellular metabolism." (PMID 37280670, 2023). "We report our institutional case of a diffuse astrocytoma with progression to secondary glioblastoma and concurrent IDH1/IDH2 mutations." (PMID 37077830, 2023). "On the other hand, IDH1/2 wild-type subtypes are more common in glioblastomas and are associated with poor outcome." (PMID 37749078, 2023). "Fifteen patients had IDH1 mutation (7 anaplastic oligodendroglioma, 4 anaplastic astrocytoma, and 4 glioblastoma)." (PMID 37341199, 2023).
glioblastoma (continued). "A significant insight into their biology and variable clinical behavior began to emerge when isocitrate dehydrogenase 1 and 2 (IDH1/2) mutations were discovered in 10% of glioblastomas (GBMs) and subsequently in a large proportion of LGAs2." (PMID 36841881, 2023). "Since the publication of an anecdotal case report in 2015 in a patient with IDH-1 wild-type glioblastoma-associated epilepsy, an increasing number of observational small studies exploring the efficacy of PER in BTRE have been published." (PMID 36831869, 2023). "IDH2 mutation at R172 (R172K) residue is found only in 3% of WHO grade-II and -III astrocytomas, oligodendrogliomas, and secondary glioblastomas, whereas IDH1 mutation at R132 (R132H) affects 70% of these cancers." (PMID 36835628, 2023). "Secondary glioblastomas and their lower-grade precursors are frequently associated with driver mutations of IDH1." (PMID 36768856, 2023). "It had also been reported that IDH1 mutation promoted glioblastoma cell proliferation and migration by inducing EMT33." (PMID 37863960, 2023). "The analysis showed that age (> 45 years), WHO grade (G4), pathological type (glioblastoma multiformes), and IDH1 mutation status (wild type) were statistically positively associated with high TASL expression (P < 0.05)." (PMID 37296415, 2023). "The incorporation of ADC and SWI parameters distinguished glioblastoma with IDH1 mutations with a sensitivity and specificity of 94.3% and 100%, respectively." (PMID 36912262, 2023). "A recent study in India evaluated the molecular biomarkers of brain tumours in Indian patients and reported a high prevalence of isocitrate dehydrogenase 1 (IDH1) mutation in astrocytoma and glioblastoma in these patients." (PMID 36900254, 2023). "First, 412 of the total IDH1-responsive miRNAs were linked to known human diseases, and glioblastoma was ranked as the second most relevant disease, claiming 155 disease-related miRNAs (hypergeometric, P = 2.1 × 10−30, false discovery rate 3.6 × 10−28)." (PMID 37624931, 2023). "It is important to note that the T2FMM sign has been reported in other tumor types in humans, such as IDH1‐mutated, 1p/19q co‐deleted oligodendrogliomas and IDH1 wild‐type glioblastomas." (PMID 37246729, 2023). "It has also been reported that glioblastoma location correlates with specific genetic mutations in patients with frontal glioblastoma associated with isocitrate dehydrogenase 1 (IDH-1) mutations, which cause changes in DNA methylation." (PMID 35745709, 2022). "This is particularly true for astrocytic tumors, e.g., the IDH1-mut glioblastoma (as diagnosed in our cohort based on the current WHO classification) will be replaced by the entity IDH1 mutated astrocytoma grade 4." (PMID 34941573, 2022). "It has PDGFRA alterations and point mutations of IDH1 and develops mainly in younger patients with secondary glioblastoma." (PMID 36532035, 2022). "Unfortunately, our approach has shed light on the fact that the Warburg phenotype cannot be reversed by simply introducing the IDH1 mutation in the parental glioblastoma phenotype." (PMID 36344581, 2022). "In subsequent studies, IDH1 mutation was found to be a fundamentally important element in the natural course of the disease, especially in patients with glioblastomas." (PMID 35741254, 2022). "IDH1 mutation (R132) was used to distinguish glioblastoma grade and predict prognosis as a significant marker." (PMID 35488886, 2022). "Many factors impact survival in patients with glioblastoma, including age, Karnofsky Performance Status, postoperative chemoradiation, IDH1/2 mutation status, MGMT promoter methylation status, and extent of resection." (PMID 35156038, 2022).
glioblastoma (continued). "IDH1 mutation leads to a distinct metabolite profile, pathway alterations, and gene expression patterns in astrocytoma, oligodendroglioma, and glioblastoma." (PMID 34941573, 2022). "Jayapalan reported a rosette-forming glioneuronal tumor with IDH1 mutation, which recurred in situ and progressed to glioblastoma 6 years after partial resection." (PMID 36531047, 2022). "The IDH1 mutant is associated with better prognoses for patient survival than the IDH1 wild-type that is common to anaplastic astrocytoma and glioblastoma." (PMID 35053475, 2022). "Patients with IDH1/2-wildtype glioblastomas harboring CDKN2B, EGFR, and TERT promoter mutations who underwent GTR were associated with improved OS when compared to other EOR in the FDR-adjusted analysis." (PMID 35156038, 2022). "We successfully introduced the IDH1 c.395G > A point mutation heterozygously in a primary patient-derived glioblastoma cell line (HT7606) using CRISPR/Cas9." (PMID 35628596, 2022). "Recurrent IDH1 mutations affecting codon R132 were initially identified in glioblastoma multiforme (GBM), where the mutation showed a significant prevalence in secondary GBM1." (PMID 34997121, 2022). "IDH-WT glioblastoma is an aggressive and diffuse astrocytic glioma that lacks mutations in IDH1, IDH2, and histone H3 genes." (PMID 36553127, 2022). "TERT promoter (TERTp) mutations are the most common non-coding mutations in cancer, including the majority of IDH1 wild-type (IDH1-WT) primary glioblastoma (GBM)." (PMID 36130485, 2022). "Whole-exome sequencing and pathological examination revealed glioblastoma, IDH1 wild type, PTEN deficient, TERT mutated, NF1mutated, MGMT unmethylated." (PMID 36271359, 2022). "The reason is that proneural subclass is majorly associated with secondary glioblastomas (85%) having IDH1 gene mutations, whereas other three subclasses are linked to primary glioblastomas showing less (5%) or no alteration in IDHI gene." (PMID 36185622, 2022). "Not only AML, but several different tumor types–such as astrocytoma and glioblastoma–carry mutations of IDH1/2, underlying the critical role of these enzymes in tumorigenesis." (PMID 35740380, 2022). "Studies have found that the mutation’s frequency of IDH1 genes in oligodendroglioma, astroglioma, and secondary glioblastoma is as high as 60%–80%, but in primary glioblastoma almost absent in the tumor." (PMID 36091829, 2022). "A phase 1b/2 clinical trial (NCT03684811), investigating the effect of the 5-azacytidine in combination with Olutasidenib on glioblastoma patients with IDH1 mutations is ongoing, and the results are eagerly awaited." (PMID 35806153, 2022). "To date, a wealth of studies has identified the typical genetic alterations that occur in glioblastoma: Mutations in IDH1 or, for paediatric glioblastomas, the two frequently occurring histone H3." (PMID 34234357, 2021). "A recent Phase I/II study of DSF and Cu++ with concurrent radiation therapy and TMZ for newly diagnosed glioblastoma demonstrated promising preliminary efficacy for a subset of tumors with IDH1, BRAF, and NF1 mutations." (PMID 34731160, 2021). "U87MG glioblastoma cells transfected with a pCMV6 plasmid encoding for R132H IDH1 also accumulated 2HG." (PMID 34854890, 2021). "Younger patients with glioblastoma have better outcomes when IDH1/2 mutations and MGMT promoter methylation are present, so an accurate diagnosis is critical for these patients." (PMID 33506208, 2021). "The survival time of glioblastoma patients with only an IDH1 mutation was shorter than for patients with both IDH1 mutations and MGMT methylation." (PMID 34638714, 2021). "This is the case of the treatment of cancers that present mutations in IDH1 or 2, mainly glioblastoma multiforme (GBM) or acute myeloid leukaemia (AML)." (PMID 33915900, 2021).
glioblastoma (continued). "Regarding the molecular features of glioblastoma, missing data is mainly related to later implementation of molecular markers into the diagnostic set-up of glioblastoma, for example, IDH1 mutation status." (PMID 33506201, 2021). "We consider the IDH1(R132H) as a “therapeutic mutation” due to its ability to improve progression free and overall survival in glioblastoma patients." (PMID 34564387, 2021). "Although promising, the level of evidence is low, consisting of small, highly selective, and retrospective series with potential confounding biases related to glioblastoma biology (IDH1/2 mutations status, MGMT promoter methylation status)." (PMID 34200799, 2021). "Glioblastoma patients whose tumors carried an IDH1 mutation, MGMT promoter methylation and low HOTAIRM1 expression showed the longest overall survival." (PMID 34584066, 2021). "Because IDH1 mutation is considered a major prognosticator in glioblastoma, we report a correlation between CD204+TAMs and CD4+TILs with IDH1 mutation." (PMID 35201470, 2021). "Second, glioblastoma patients with IDH1 mutation and MGMT promotor methylation are significantly associated with long-term survival." (PMID 34459971, 2021). "IDH1 mutation is an important prognostic hallmark of secondary glioblastomas, and is associated with the increase of overall survival 28,29." (PMID 33391433, 2021). "They discovered three distinct and reproducible imaging subtypes of glioblastoma with differential clinical outcome and underlying molecular characteristics, including IDH1 and EGFRvIII." (PMID 34164563, 2021). "Isocitrate dehydrogenase 1 (IDH1) gene mutations were high frequently detected in human cancers particularly in secondary glioblastomas (>70%)." (PMID 35996504, 2021). "Among patients less than 50 years of age, a significant difference was observed in recurrence-free interval between glioblastomas with IDH1 mutation and wildtype IDH1 (p-value = 0.014)." (PMID 34257620, 2021). "The close association between miR-411 and KPS and IDH1 of patients in the present study implies the potential involvement of miR-411 in the progression and prognosis of glioblastoma." (PMID 34606414, 2021). "The IDH1 mutation occurs at a hot spot of the IDH1 gene and is the main driver of IDH1mt glioblastoma that make up 5% of all glioblastoma tumors." (PMID 33810170, 2021). "IDH mutations often occur in LGGs patients with incidences of up to 75%, while the mutation frequency of IDH1 is lower in glioblastoma (12%)." (PMID 34961815, 2021). "Of the 226 patients who had IDH1 mutation testing performed, 15 (6.6%) had an IDH1-mutant glioblastoma." (PMID 34988453, 2021). "In a significant proportion of glioblastoma, isocitrate dehydrogenase 1 (IDH1) is mutated, causing metabolic rewiring, and all cancer cells use OXPHOS for ATP and ROS production." (PMID 33810170, 2021). "IDH1/2 inhibitors are active in IDH1/2-mutated acute myeloid leukemia, but demonstrate limited efficacy in glioblastomas carrying IDH1/2 genetic alterations." (PMID 34681592, 2021). "The majority of glioblastomas is defined as primary, mostly with wild-type isocitrate dehydrogenase 1 (IDH1), whereas most of the secondary cases harbor mutations in IDH1." (PMID 34067762, 2021). "In a previous study from our institution on 106 glioblastoma patients with a partly overlapping patient population, only two cases had IDH1 mutations." (PMID 33742279, 2021). "In this study, we evaluated the impact of MGMT promoter methylation and IDH1 mutation on the recurrence-free interval in patients with glioblastoma treated with different treatment modalities (radiotherapy and different types of chemotherapies)." (PMID 34257620, 2021). "Several studies showed that IDH1 mutation are very frequent in secondary glioblastoma (>80%) but very rare in primary glioblastoma (<5%)." (PMID 34066132, 2021).